HPSE (heparanase)
Diseases named in the same sentence as HPSE in open-access papers (continued):
Sharing a sentence is not in itself a finding about the gene and the disease.
tumor (continued). "The significance of this process in cancer has yet to be established but, if confirmed, would highlight the diversity of heparanase functions in tumor promotion." (PMID 25105093, 2014). "Most studies investigating heparanase have focused on its regulated expression at different stages of cancer progression, and its overexpression in tumor cells has also been reported to correlate with metastatic potential and poorer prognosis." (PMID 25549223, 2014). "Both over-expression and silencing of the heparanase gene clearly indicated the involvement of heparanase in tumor invasion, metastasis and angiogenesis." (PMID 24632672, 2014). "It is also the case in xenograft animals that overexpression of heparanase in low-metastatic tumor cells confers a highly invasive phenotype." (PMID 24632672, 2014). "The modification of HS chains in the ECM to liberate stored signaling molecules in the tumor microenvironment is a mechanism that heparanase and the sulfatases have in common." (PMID 25105093, 2014). "Using tissue microarrays with samples from over 150 PNET patients, staining intensity of heparanase (by IHC) significantly correlated with tumor stage, higher tumor grade (as defined by tumor mitotic activity), and presence of distant metastasis." (PMID 25105093, 2014). "This has previously been demonstrated in a number of studies which have shown that heparin reduces tumor metastasis rates by inhibiting heparanase." (PMID 25187827, 2014). "These transcription binding factors are proved previously that can couple with heparanase promoter and play an important role in tumor invasion and metastasis by modulating the remodeling of ECM." (PMID 24632672, 2014). "Significant decrease of invasive capacity was observed after incubation of cells with OGT2115, implying that the increase in tumor cell invasion after treatment with 5-aza-dC is due to the induction of heparanase expression." (PMID 24632672, 2014). "Treatment of MCF-7 cells with 5-aza-2′-deoxycytidine (5-aza-dC), a potent demethylating agent, results in induction of heparanase expression and higher invasion potential in vitro and leads to an advantage of tumor formation in vivo." (PMID 24632672, 2014). "It has been demonstrated that degradation of HS chains by heparanase 1 (HPSE-1) reveals cryptic HS fragments that play a significant role in controlling tumor cell growth and metastasis." (PMID 25140302, 2014). "The disruption of GAGs modification by heparanase was shown to facilitate tumor cell invasion angiogenesis and metastasis." (PMID 25506919, 2014). "Despite raising the importance of tumor type, stage, and role of heparanase in particular tumor microenvironment, other groups also found heparanase expression to be linked to poor prognosis." (PMID 25105093, 2014). "The mean level of HPSE mRNA expression in HCC tumor tissues was significantly increased compared with corresponding NTST and healthy NLT (all P < 0.01, respectively)." (PMID 25149140, 2014). "Therapeutic targeting of heparanase in cancer thus has the potential to interfere with exosome-mediated tumor-host crosstalk thereby blocking tumor progression and metastasis." (PMID 26082317, 2013). "In functional assays, exosomes from heparanase-high cells stimulated spreading of tumor cells on fibronectin and invasion of endothelial cells better than did exosomes from heparanase-low cells." (PMID 26082317, 2013). "Although we were not able to affirm a significant correlation to overall survival we revealed the link of HPSE expression to a higher rate of lymph node invasion, hence a more aggressive tumor type." (PMID 23704979, 2013). "Heparanase (HPA), a mammalian endo-beta-D-glu-curoxnidase, has previously been shown to be a key enzyme in the metastatic potential of tumor-derived cells and cells of the immune system." (PMID 23442498, 2013). "Heparanase is a potent modulator of tumor behavior due to its protumorigenic, proangiogenic, and prometastatic activities." (PMID 23984412, 2013).
tumor (continued). "Heparanase is a potent tumor modulator due to its protumorigenic, proangiogenic, and prometastatic activities." (PMID 23984412, 2013). "Some studies showed that certain HPSE inhibitors, such as polysaccharides, siRNA, and polypeptide antibodies, had the potency of suppressing tumor invasion, metastasis and angiogenesis." (PMID 23308126, 2013). "One compound that seems to modulate the level of nuclear syndecan-1 in several tumor types is heparanase when simultaneously present in the nucleus." (PMID 24392351, 2013). "Increased heparanase increased exosome secretion, changed protein cargo, and stimulated spreading of tumour cells on fibronectin and invasion of endothelial cells (presented by C. Thompson, University of Alabama, Birmingham, USA)." (PMID 26082318, 2013). "For this reason, HPSE is regarded as a promising and crucial target molecule for anti-tumor investigations." (PMID 23308126, 2013). "Our results are also consistent with previous findings that heparanase localized to lysosomes in fibroblasts, osteoblasts, osteo (chondro) clasts, and tumor cells." (PMID 23509775, 2013). "This work also shows that heparanase expression is related to higher incidence of metastasis and the size of the primary tumor." (PMID 23984412, 2013). "Heparanase is an endoglycosidase, degrading heparan sulfate proteoglycans, being a critical mediator of tumor cell proliferation, angiogenesis, invasion and metastasis." (PMID 23344048, 2013). "Heparanase is an endoglycosidase that degrades heparan sulfate in the tumor microenvironment, cell surfaces, and vessel wall." (PMID 22902885, 2012). "To support the tumor suppressor role of this gene, we further investigated the genetic alterations and expression changes of the HPSE gene in HCCs and evaluated their clinical implications." (PMID 22952874, 2012). "The elevation of heparanase levels in human tumors, together with the prothrombotic state of most neoplasms, suggests possible clinical relevance of the procoagulant function of heparanase." (PMID 23908827, 2012). "This HPSE RNAi leads to slow growth, reduced clonogenic capacity, and invasive potential of aggressive tumor cell lines." (PMID 22719918, 2012). "Preliminary Western blotting data supported the findings that PG545 reduces heparanase protein expression in 4T1 breast primary tumor homogenates." (PMID 23300607, 2012). "Acting together heparanase and selectin facilitate tumor cell arrest, extravasation, and metastasis." (PMID 22902885, 2012). "The semi-quantitative score (conducted independently by two researchers in a blinded fashion) for heparanase staining was between 36–43% higher in diseased lung tissue compared with tumor tissue in 4T1-inoculated animals." (PMID 23300607, 2012). "In several carcinomas, most intense heparanase staining was localized to the invasive front of the tumor, supporting a role for heparanase in cell invasion." (PMID 23908827, 2012). "The poor therapeutic effects with HPSE inhibitors beg for a fresh thinking on the role of HPSE in tumor progression." (PMID 22952874, 2012). "The result showed a small but significant correlation between HPSE copy number and mRNA levels in tumor tissues (r = 0.23, P = 0.013)." (PMID 22952874, 2012). "Compound 6 appears to be the best sample in term of biological activities, it inhibits heparanase, P-selectin and is an anti-metastatic drug for different tumours." (PMID 22902885, 2012). "Elevated expression of HPSE in tumor cells dramatically enhances their growth, angiogenesis, and metastasis to bone or brain." (PMID 22719918, 2012). "HPSE protein level was also remarkably reduced in 66.3% (53/80) of tumor tissues, which was correlated with tumor grade." (PMID 22952874, 2012). "The clinical significance of the enzyme in tumor progression emerges from a systematic evaluation of heparanase expression in primary human tumors." (PMID 23908827, 2012).
tumor (continued). "Given the impact of heparanase on tumor angiogenesis and metastasis and the anti-metastatic activity of HS mimetics/heparanase inhibitors, PG545 was investigated in the 4T1 mastectomy model using sorafenib as an antiangiogenic comparator agent." (PMID 23300607, 2012). "Given the multitude of functions of heparanase, systemic heparanase amplification can perpetuate tumor-promoting autocrine, paracrine, and growth factor signalling, making heparanase inhibitors potentially effective against invasive cancers." (PMID 23300607, 2012). "In tumor and lung tissue, heparanase expression was approximately 30% lower in the PG545-treated animals compared with the vehicle-treated animals." (PMID 23300607, 2012). "Studies of tumor cells and T lymphocytes have shown that heparanase expression can be induced by the transcription factor early growth response 1 (EGR1) which, itself, is dependent on ERK1/2 activity." (PMID 23300607, 2012). "The result exhibited a lower staining score of HPSE protein in 53 (66.3%) HCC tissues than in their matched non-tumor adjacent tissues." (PMID 22952874, 2012). "Heparanase is preferentially expressed in human tumors and its over-expression in tumor cells confers an invasive phenotype in experimental animals." (PMID 23908791, 2011). "At the cellular level, both tumor cells and cells that comprise the tumor microenvironment (i.e. endothelial, fibroblasts, tumor-infiltrating immune cells) are likely to be affected by heparanase." (PMID 23908791, 2011). "Taken together, our findings demonstrate the tumor angiogenesis and the role of heparanase in ccRCC on the basis of clinical and pathological parameters, thus contributing to the basic understanding of the most common malignant tumour of adult kidney." (PMID 22133010, 2011). "Subsequent studies demonstrated that the heparanase DNA sequences derived from normal and tumor cells (which undoubtedly represent the same gene) are unique." (PMID 23908791, 2011). "In head and neck carcinoma, high levels of heparanase were associated with increased lymphatic vessel density (LVD), increased tumor cell invasion to lymphatic vessels, and increased expression of VEGF-C,54 a potent mediator of lymphatic vessel formation." (PMID 23908791, 2011). "Heparanase up-regulation correlates with increased tumor vascularity and poor postoperative survival of cancer patients." (PMID 23908791, 2011). "M402 is a rationally engineered, non-cytotoxic heparan sulfate (HS) mimetic, designed to inhibit multiple factors implicated in tumor-host cell interactions, including VEGF, FGF2, SDF-1α, P-selectin, and heparanase." (PMID 21698156, 2011). "Vlodavsky and colleagues have published extensively on the role of heparanase, a heparin sulfate-cleaving enzyme, in tumor progression." (PMID 21698156, 2011). "Heparanase-mediated degradation of HS is involved in tumour angiogenesis and metastasis, making it a major target for cancer research." (PMID 21285983, 2011). "Expression of heparanase was observed in 96 tumour samples (75%), conversely in 25 adjacent normal tissues (19.5%) (P < 0.0001)." (PMID 22133010, 2011). "These and other results strongly suggest that heparanase and HSPGs act synergistically within the tumor microenvironment to enhance tumor growth, implying that inhibitors of heparanase will benefit cancer patients." (PMID 23908791, 2011). "Heparanase over-expression is prevalent in ccRCC, which promotes tumor angiogenesis and indicates worse prognosis." (PMID 22133010, 2011). "Proangiogenic potency of heparanase was established clinically and in several in-vitro and in-vivo model systems, including wound-healing, tumor xenografts, Matrigel plug assay, and tube-like structure formation." (PMID 23908791, 2011). "Heparanase activity is also responsible for the egress of metastatic tumor cells and other blood-borne cells from the vasculature." (PMID 20652010, 2010).
tumor (continued). "This study addresses the mechanism(s) whereby expression of heparanase by tumor cells enhances systemic osteolysis." (PMID 20200931, 2010). "Overall, these results suggest a model where heparanase upregulation by tumor cells degrades heparan sulfate chains and enhances syndecan-1 shedding." (PMID 20200931, 2010). "We thank Elizabeth Navarro (ImClone, New York, NY) for help with the heparanase activity determinations, Robert A Skinner for histology, and Yan Huang for tumor biology (UAMS)." (PMID 20200931, 2010). "Heparanase released by the tumor cells degrades HS both in the extracellular matrix and at the cell surface." (PMID 19527490, 2009). "Further, increased expression of heparanase is correlated with the high metastatic capacity of tumor cells." (PMID 19527490, 2009). "Over expression of heparanase, the predominant HS degrading enzyme, in transgenic mice and tumor tissues resulted in pronounced structural alterations of HS." (PMID 19360105, 2009). "This feature is influenced by several biological molecules, including soluble factors secreted by tumor cells, such as heparanase (HPSE)." (PMID 19715595, 2009). "Here we investigate the sub-cellular distribution of syndecan-1, FGF-2, FGFR-1 and heparanase in malignant mesenchymal tumor cells, and explore the possibility of their coordinated translocation to the nucleus." (PMID 19802384, 2009). "Heparanase can facilitate breakdown of the extracellular matrix which aids tumor cell migration and releases factors that promote tumor growth, angiogenesis and metastasis." (PMID 19305494, 2009). "This role of heparanase is supported by findings that heparanase inhibitors can inhibit tumor growth and metastasis." (PMID 19305494, 2009). "It was recently discovered that heparanase can also enhance shedding of the syndecan-1 heparan sulfate proteoglycan from the surface of tumor cells." (PMID 19305494, 2009). "Given that heparanase promotes an aggressive tumor phenotype and that it can also regulate the location of syndecan-1, we examined the effect of heparanase expression on syndecan-1 localization within the nucleus." (PMID 19305494, 2009). "In many cases, heparanase induction correlated with increased tumor metastasis, vascular density, and shorter post operative survival rate, thus providing a strong clinical support for the pro-metastatic and pro-angiogenic function of the enzyme." (PMID 18545691, 2008). "Overexpression of heparanase cDNA in tumor cells with low metastatic potential confers a high metastatic potential after injection of these cells into the experimental animals." (PMID 18647407, 2008). "In light of the results of other studies of heparanase expression in various tumours heparanase activation appears to be a crucial step for a tumour to become systemic." (PMID 11953884, 2002). "There is a trend towards heparanase expression in metastasising tumours as compared to locally growing tumours." (PMID 11953884, 2002). "Its expression is upregulated in a number of metastatic tumour cell lines and transfection of tumour cells with heparanase cDNA conferred a highly metastatic phenotype." (PMID 11953884, 2002). "Heparanase is expressed in cell lines derived from primary tumours as well as from metastatic sites." (PMID 11953884, 2002). "Consistent with its molecular capabilities heparanase has been shown to stimulate wound healing and tumour angiogenesis in vivo." (PMID 11953884, 2002). "However, under acidic conditions, with optimal activity at a pH of 5–6, such as during inflammation or tumor progression, HPSE becomes active." (PMID 41301515, 2025). "A key venue by which heparanase exerts its multiple effects on cells and tissues is by regulating the bioavailability of HS-bound growth factors, chemokines, and cytokines, thereby mediating tumor-host crosstalk and tissue remodeling." (PMID 40940793, 2025).
tumor (continued). "In addition, EXOs from hypoxic tumor cells, carrying elevated levels of heparanase cargo, significantly promote the formation of ECs tubes, consistent with the known role of heparanase in promoting angiogenesis." (PMID 40486870, 2025). "Notably, the role of PHF23 in promoting tumor metastasis is similar to the function of heparanase in tumor invasion." (PMID 41268576, 2025). "The roles of HS and its modifying enzymes (such as heparanase and sulfatases) have emerged as a critical focus of carcinogenesis and related cancer therapeutic research due to their influence on tumor progression, metastasis, angiogenesis, and the tumor microenvironment." (PMID 40564190, 2025). "Interestingly, inhibition of heparanase—an enzyme involved in extracellular matrix degradation and tumor progression—significantly mitigates inflammation-driven thrombosis." (PMID 40277915, 2025). "Importantly, high heparanase expression correlates with poor prognosis, higher tumor grade, and increased metastasis in many cancers (e.g., breast, colon, lung, pancreatic, bone sarcomas, and hematologic malignancies)." (PMID 40940793, 2025). "Moreover, overexpression of heparanase (HPSE), a β-1,4 HS chain-cleaving enzyme of HSPGs, is involved in tumor growth-promoting mechanisms, angiogenesis, and metastasis." (PMID 40723905, 2025). "Additionally, systematic assessment of relative heparanase inhibition efficacy among different LMWHs remains inadequately characterized, despite this enzyme’s critical role in tumor progression and metastasis." (PMID 40143176, 2025). "This comprehensive review examines the expanding therapeutic potential of heparin derivatives in oncology, extending beyond traditional anticoagulation mechanisms to include direct antineoplastic effects, heparanase inhibition, and modulation of tumor microenvironment interactions." (PMID 40143176, 2025). "The collective expression of degradative enzymes, such as MMPs, ADAMs, ADAMTS, plasminogen activation system components, cathepsins, and HPSE in the tumor microenvironment enables invading cells to migrate inside the ECM and then disseminate into the circulation." (PMID 41301515, 2025). "The advantage of using a syngeneic mouse model vs. immunodeficient mice is the existence of an intact, fully active immune system that plays an important role in tumor progression and likely also in the anti-tumorigenic effect of heparanase-inhibiting compounds." (PMID 38334603, 2024). "Additionally, promising therapies to reduce its elimination to limit tumor progression include heparanase and MMP inhibition, synthetic proteoglycans mimicking SDC1, and strategies targeting growth factor interactions." (PMID 39728992, 2024). "Heparanase-1 enzyme activity plays a prominent role in tumor microenvironment modulation." (PMID 36680276, 2023). "Likewise, by entering the nucleus and degrading nuclear syndecan‐1, heparanase mediates HAT activation and transcription of genes associated with an aggressive tumor phenotype." (PMID 37547889, 2023). "Heparanase promotes tumor development and progression and is upregulated in tumors found in the abdominal/pelvic cavity, whose radiation treatment may result in radiation nephropathy." (PMID 36979689, 2023). "The emerging premise is that heparanase expressed by tumor cells, immune cells, endothelial cells, and other cells of the tumor microenvironment is a key regulator of the aggressive phenotype of cancer, an important contributor to the poor outcome of cancer patients and a valid target for therapy." (PMID 37547889, 2023). "HPSE has a role in tumor invasion, acting on HSPGs on the cell surface." (PMID 36980765, 2023).